MMP9 (matrix metallopeptidase 9)
Diseases named in the same sentence as MMP9 in open-access papers (continued):
Sharing a sentence is not in itself a finding about the gene and the disease.
tumor (continued). "For example, MMP-9 and CG can degrade the extracellular matrix to prepare for tumor metastasis; 2) NETs capture circulating tumors cells (CTCs), cells that are shed from the primary tumor site or metastasis, entering the vasculature, and thus escape from immune attack." (PMID 34869390, 2021). "Moreover, treatment notably upregulated the mRNA expression levels of GSK-3β, E-cadherin, Bax, Caspase-3, and Caspase-9 and the Bax/Bcl-2 ratio but substantially downregulated β-catenin, N-cadherin, MMP-2, MMP-9, Snail, and Cyclin D1, especially Ki-67 and N-cadherin, in tumour tissues." (PMID 34539401, 2021). "Finally, immunofluorescence staining performed by using anti-CD31, -αSMA, -VEGF, -MMP-2 and -MMP-9 antibodies demonstrated a significant reduction of tumor angiogenesis and capability of tumor invasion, when HPR was administered through NL-HPR and, at a greater extent, through NGR-NL-HPR." (PMID 34577553, 2021). "Additionally, NF-κB also regulates extracellular matrix through MMP9 and promote tumor invasion." (PMID 34685753, 2021). "Besides, down-regulation of MMP2 and MMP9 reduced tumor metastasis too." (PMID 34051801, 2021). "In vitro studies revealed that silencing CDCA3 could impair the migration ability of tumor cells via down-regulating EMT-related proteins such as MMP9 and Vimentin and inhibit tumor cell growth via arresting cells in the G1 cell cycle phase through regulating cell cycle related proteins like p21." (PMID 33980246, 2021). "IL-17 may increase MMP-9 production to promote angiogenesis and tumour growth." (PMID 33923108, 2021). "Therefore, TFEB might regulated MMP2 and MMP9 expression through lysosomal biogenesis in the tumor environment." (PMID 33732651, 2021). "Interestingly, MMP9 was upregulated in our EC tumor samples." (PMID 34400640, 2021). "In addition, the antiangiogenic activity of fucoidan was confirmed in MDA-MB-231 cells through the reduction of VEGFA, IGF-I, MMP-2, and MMP-9 levels, basic fibroblast growth factor (bFGF), and the blockade of the adhesion and extravasation of tumor tissue to vascular endothelial cells." (PMID 34200897, 2021). "And previously, inhibition of MMP9 could modulate immunosuppression in tumor." (PMID 33643387, 2021). "Similarly, a high number of tumor-associated macrophages lead to an increased production of angiogenic factors such as VEGF, PDGF, IL-8, TNF-α und bFGF and an enhanced expression of angiogenesis promoting enzymes such as MMP-2, MMP-7, MMP-9 and MMP-12." (PMID 34821752, 2021). "In the tumor tissue of LF group, we observed that the expression of MMP-9 was higher than that of control group in liver tissue while there was no statistical difference in the MMP-2 expression between two groups, which may be related to the characteristics of tumor cell lines." (PMID 34819565, 2021). "Moreover, MDSCs-produced cytokines and chemokines, such as TGF-β, VEGFA, S100A8/A9, and MMP-9, might play important role in pre-metastatic niche formation through facilitating angiogenesis and tumor cell invasion." (PMID 35004667, 2021). "Similarly, other studies confirmed that the activity of MMP-2 might be associated with the tumour stage, while mRNA expression of MMP-9 was evaluated in regard to tumour recurrence." (PMID 33923108, 2021). "Importantly, similar to short-term Olaparib treatment, RT-PCR analysis of parental and Olaparib-resistant A2780, OVCAR8, and PEO1 cells showed mRNA upregulation of several essential tumor-promoting genes, such as MMP9, VEGFA, CCND1, and BCL2L1, which are known STAT3 target genes." (PMID 34956861, 2021). "Moreover, TAMs may cause changes in the tumor microenvironment by enzymes secretion, for example, MMPs, including MMP7, MMP2 and MMP9." (PMID 34203461, 2021). "Furthermore, MMP-9 is known to favor tumor angiogenesis, and its reduced expression might, therefore, represent one factor contributing to the low microvessel density observed in CDV-infected DH82 xenografts." (PMID 33808256, 2021).
tumor (continued). "In addition, survivin, NF-κB, and MMP-9 expression was prevented in tumor tissues." (PMID 34073059, 2021). "Moreover, knockdown of MMP-9 could markedly suppress OSCC cell xenografted tumor growth, proliferation, lymph node metastasis, and angiogenesis in the nude mouse tongue-xenografted model." (PMID 33828938, 2021). "Overexpression of MMPs in tumor cells will enhance degradation of the basement membrane to facilitate invasion of nearby blood vessels, followed by extravasion to distant tissues to seed new metastatic sites and tumor cells mainly express MMP-9 instead of MMP-2 in HCC47." (PMID 34819565, 2021). "Indeed, a selective inhibition of STIM/Orai isoforms could decrease MMP-9 secretion, a major secreted matrix metalloproteinase from neutrophils, which is involved in angiogenesis and tumor growth." (PMID 34201758, 2021). "However, an altered MMP-9/TIMP-1 ratio is assumed to influence tumor progression." (PMID 33808256, 2021). "In addition, it could inhibit the migration of tumor cells via the downregulation of MMP-9 and Notch-1 level." (PMID 34443415, 2021). "The findings on the permissive role of Ankrd2 in spheroid formation and in the modulation of MMP2 and MMP9 activities, as well as the evidence that Ankrd2-depleted clones lose the ability to form spheroids, hint at a positive role for Ankrd2 in triggering metastases and tumor spreading." (PMID 33419058, 2021). "Similarly, TAMs are associated with increased activity of MMP-2 and MMP-9 from PDAC cells and a decrease in E-cadherin expression, which may promote the ability of tumor cells to metastasize." (PMID 35008355, 2021). "Hypoxia leads to the detachment of tumor cells by down-regulating cell adhesion molecules, and by up-regulating the molecules involved in the degradation of integrin and cell attachment components such as MMP-9 and urokinase-type plasminogen activator receptor (uPAR)." (PMID 34639215, 2021). "Moreover, the release of neutrophil extracellular traps (NETs), which are structures formed by DNA and granular proteins and are released upon stimulation, is linked to the N2 phenotype, as NETs contain proteins that support tumor growth, such as matrix metallopeptidase-9 (MMP-9) and cathepsin G." (PMID 34200529, 2021). "In addition, silencing of SPNS2 increased MMP2 and MMP9 expression, while overexpression of SPNS2 decreased the MMP2 and MMP9 expression, which could degrade the extracellular matrix and stimulate tumor invasion and metastasis." (PMID 34249729, 2021). "Among 23 human MMPs, MMP 2 and MMP-9 play a critical role in tumor invasion and angiogenesis because of their ability to degrade type IV collagen of basement membrane which forms the first barrier in the process of invasion, however, MMP-9 is 25 times more potent than MMP-2." (PMID 34707964, 2021). "In addition, the overexpression of TIMP-1 correlates with the elevated expression of MMP-9, and may stimulate tumor growth and malignant transformation as well as inhibit tumor cell apoptosis." (PMID 34071492, 2021). "Therefore, at the tumor site, MMP-9 produced by cancer cells combines with that synthesized by normal inflammatory, immune, parenchymal or stromal cells; this leads to a dramatic rise of MMP-9 protein levels which is not paralleled by an increase in TIMP synthesis." (PMID 32630531, 2020). "In brief, MMP-9 may act as a tumor promoter in many solid tumors." (PMID 32382550, 2020). "Therefore, MMP-9 may be involved in other stages besides atherosclerotic plaque progression, such as tissue remodeling, inflammation, tumor invasion, wound healingc and other physiological processes can increase its serum value." (PMID 33003997, 2020). "TAM repolarization may be also induced by natural compounds, such as Onionin A, from onions and Deoxyschizandrin, from berries, that can abrogate pro-tumor activation of M2 macrophages and can reduce the production of the tumor-promoting factors (MMP9, CCL5, and VEGF)." (PMID 32354198, 2020).
tumor (continued). "On these bases, OPN and MMP-9 could be considered biomarkers of tumor progression." (PMID 32392801, 2020). "Moreover, this reduction also inhibits MMP-9 and thus tumor invasion." (PMID 33240810, 2020). "Our results showed that JAM-B can activate the c-Src/MMP9 pathway directly, has important clinical implications because it involves novel pharmacologic targets that may be targeted to reduce tumor neuroinvasion and to improve the survival of patients with PanCa." (PMID 32231730, 2020). "The decrease of serum TNF-α (tumor necrosis factor), IL-8 (interleukin-8), MMP-2 (matrix metalloprotein-2) and MMP-9 (matrix metalloprotein-9) of the treated C57BL/6 mice was correlated with the action pathway of RGDV-gemcitabine inhibiting the metastasis of the planted tumor towards lung." (PMID 32978501, 2020). "Thus, targeting MMP-9 expression is a potential strategy to regulate tumor metastasis." (PMID 31893611, 2020). "Furthermore, neutrophils are able to sustain tumor progression through the release of proangiogenic factors such as VEGF and MMP9 and, by maintaining an immunosuppressive tumor microenvironment through the expression of the arginine-consuming enzyme Arg1 and ROS production." (PMID 32580431, 2020). "This indicates that macrophages exposed to low levels of TNIIIA2 in the early stage of the tumor lesion establishment might contribute to the elicitation of an aggressive malignant phenotype from GBM cells via enhanced MMP-9 expression and subsequent digestion of TN-C and exposure of TNIIIA2 region." (PMID 33362799, 2020). "Elevated MMP9 cytoplasmic and stromal staining were associated with high tumour grade (p < 0.0001), poor Nottingham Prognostic Index (NPI) (p < 0.0001), hormone receptor negativity (p < 0.01), among IHC subtypes associated with TNBC and HER2 + tumours (p = 0.002)." (PMID 32445177, 2020). "Furthermore, tumor-promoting neutrophils in BC cells are also characterized by high expression of matrix metalloproteinases-9 (MMP-9), which was found to cleave CXCL-5, potentiating its action in neutrophil recruitment as a positive feedback function in tumors." (PMID 32849640, 2020). "The expression levels of p-AKT, NF-κB, MMP9/2 were only quantified by IHC in the tumor tissues, and further studies may employ western blot assay to determine the levels of these proteins in the tumor tissues." (PMID 32117722, 2020). "Moreover, NETs can further provide NE and/or MMP-9 to promote tumor cell growth." (PMID 32422991, 2020). "Therefore the down regulation of serum MMP-2 and MMP-9 may be a possible action pathway of RGDV-gemcitabine inhibiting tumor metastasis." (PMID 32978501, 2020). "And also, inhibition of MMP9 could modulate immunosuppression in tumor." (PMID 32509418, 2020). "Since MMP2 and MMP9 are involved in the continued growth of the tumor and metastasis, coupled with the fact that high expression of both is related to poor patient survival in various types of cancers, an OV that targets these markers could be of high clinical value." (PMID 33167307, 2020). "Besides, we have shown that not only MMP3 but also MMP9 were crucial in LuM1 tumor progression." (PMID 32260433, 2020). "In addition to being produced by the transformed or normal cells composing the tumor mass, MMP-9 is released in a TIMP-1-free form by neutrophils or macrophages which are recruited to the tumor site during the inflammatory response that accompanies cancer development or progression." (PMID 32630531, 2020). "In contrast, tungsten changed the tumor microenvironment which enhanced parameters known to be important for cell invasion and metastasis (such as activated fibroblasts, matrix metalloproteinases (MMP9), and myeloid-derived suppressor cells) and which were associated with a poor prognosis in humans." (PMID 33203443, 2020).
tumor (continued). "Multiple tumour types have been shown to be markedly hypoxic, which may favour a pro-tumorigenic neutrophil phenotype—the increased release of neutrophil MMP-9 can promote cancer growth by enabling angiogenesis, whilst neutrophil proteases can facilitate tumour cell invasion by activating pro-MMP-2." (PMID 32053993, 2020). "In a mouse model, IRI-induced expression of MMP-9 and predisposed the growth of micro-metastases of colorectal carcinoma in the liver, while the subsequent administration of MMP-inhibitors may reduce the metastatic tumour burden." (PMID 32806712, 2020). "Moreover, MMP9 also participates in regulating tumor growth." (PMID 33659208, 2020). "Moreover, MMP9 mediates the tumor microenvironment by promoting the extravasation of tumor cells." (PMID 32905356, 2020). "The major cell type expressing MMP9 mRNA and protein were tumor‐infiltrating neutrophils, while Tgfb1 mRNA expression was mostly restricted to tumor‐infiltrating monocytes and Tgfb2, and Tgfb3 mRNA expression was mostly restricted to tumor epithelium and stroma." (PMID 31793740, 2020). "Abaza and Luqmani found that extracellular low pH could cause the secretion and activation of major proteolytic enzymes, including MMP-2, MMP-9, tissue serine protease, and gelatinase, leading to the degradation of extracellular matrix, thereby promoting tumor invasion." (PMID 32211041, 2020). "Indeed, neutrophil-derived MMP-9 could enhance tumor angiogenesis and cancer cell intravasation, thereby facilitating tumor progression." (PMID 32422991, 2020). "In one example, the protease- activatable nanoprobes have been developed by combining fluorescent dye and Fe3O4 nanocrystals through MMP-9 302, which could turn “ON” the fluorescence for tumor imaging when the peptide substrates linkers were cleaved by protease." (PMID 32292515, 2020). "Thus, there was an inverse correlation between miR-483-3p and MMP9 expression in tumor tissues." (PMID 33659208, 2020). "Additionally, FSCN1 may regulate nuclear factor-κB (NF-κB) activity, and the expression of MMP-2 and MMP-9, to promote tumor invasion and migration." (PMID 32699531, 2020). "Moreover, fluorescence-based immunohistochemistry analysis also showed that metastatic foci in lungs of SM-treated mice are characterized by a low expression of MMP-9, which can degrade extracellular matrix and, therefore, plays a crucial role in tumor cell invasion." (PMID 33327637, 2020). "Interestingly, a trend towards a negative link associated E-cadherin with MMP-9 expression in the stroma and the tumor areas (r = −0.34, p=0.14; Pearson)." (PMID 31885577, 2019). "Therefore, inhibition of CXCR4 signaling could lead to impaired neutrophil motility and ability to respond to tumour cells also as a result of altered mmp9-driven chemotaxis." (PMID 30787324, 2019). "The degrees of expression of two members of the MMP family, MMP-2 (gelatinase-A, 72 kDa) and MMP-9 (gelatinase-B, 92 kDa) were identified to be in closely related relationship with the metastasis and invasion ability of tumor cells, particularly secondary tumor growth." (PMID 30744075, 2019). "Our study suggests that MMP9 inhibition may be an important strategy in controlling the establishment of the metastatic niche, predominately early during tumorigenesis before widespread dissemination of tumor cells into circulation." (PMID 31727800, 2019). "MMPs, such as MMP-2 and MMP-9, consist of a multigene family of zinc-dependent ECM-remodeling endopeptidases that accelerates proteolytic degradation of ECM and thereby causes migration and invasion of cancer cells, which in turn results in the promotion of tumor metastasis." (PMID 31391858, 2019). "Moreover, MMP-9 overexpression is associated with tumor stage, regardless of the gender of the patients." (PMID 31311559, 2019).
tumor (continued). "While TANs can mediate tumor cell killing by releasing reactive oxygen species (ROS) and neutrophil elastase, they can also support early tumorigenesis by inducing angiogenesis through matrix metalloproteases 9 (MMP-9) and VEGF, and accelerate tumor proliferation by delivering neutrophil elastase." (PMID 31181729, 2019). "Of note, both MMP-9 and MRP family members have been linked to tumor angiogenesis, suggesting that α3β1 on tumor cells might similarly regulate paracrine stimulation of endothelial cells in the tumor vasculature." (PMID 31137641, 2019). "However, this late MMP-9 induction was lower than the early one at 1 w p.i., which may be due to the similar tumor sizes and cellular mitosis at 6 w p.i. in 4T1- vs. Py230-based primary tumors." (PMID 31921184, 2019). "Two of them, MMP7 and MMP9, were reported that higher expression of the two genes with poor prognosis of ccRCC19,20, supporting our results that higher expression of the two genes with poor survival probability, higher neoplasm histologic grade and pathologic stage." (PMID 31723226, 2019). "In addition to their immunosuppressive ability, MDSCs could contribute to tumor angiogenesis primarily via the secretion of MMP9, which increased the bioavailability of VEGF, thereby destroying angiogenic dormancy and facilitating tumor metastasis." (PMID 31297335, 2019). "Therefore, MMP-9 expression in tumour cells might play an important role in several prognostic processes." (PMID 30142200, 2018). "Apart from the influence on the viability of tumor cells, EO could affect migratory and invading properties of different tumor cells through inhibition of MMP-9, MMP-2, focal adhesion kinase (FAK), ERK1/2, and Akt/PKB activation, and partial inhibition of AP-1 and NF-kB transcriptional activities." (PMID 29757198, 2018). "Therefore, MMP-9 has been considered an important prognostic predictor in various tumours." (PMID 30142200, 2018). "As our in vitro studies revealed changes in the expression of mesenchymal proteins, Snail and Vimentin, and in the activity of MMP-2 and MMP-9 on cancer cells treated with Kp-10, we also investigated whether the Kisspeptin treatment blocks tumor metastatic behavior in vivo." (PMID 29721201, 2018). "Besides the direct influence on cancer cells, EP3 also promotes the tumor metastasis and angiogenesis by upregulating the matrix metalloproteinases (MMP)-9 of endothelial cells, which is an essential component of stroma and constitutes the tumor microenvironment." (PMID 29416671, 2018). "Hence, restraining MMP-2 and MMP-9 levels could influence the invasion and metastasis of the tumor cells, which may lead to the tumor cell apoptosis and interruption of the colon carcinogenic process." (PMID 29419740, 2018). "It is presently unknown whether this allosteric anti–MMP-9 antibody compromises the function of hemopexin domain of MMP-9 important for MMP-9 localization and substrate specificity, and whether this domain is relevant for regulation of anti-tumor T-cell mediated response in the first place." (PMID 30500835, 2018). "Other groups have instead reported the pro-tumor role exerted by neutrophils in promoting metastasis formation through the decrease of IFNγ production, the secretion of the vasculature remodelling protein MMP9 and the secretion of neutrophil-derived leukotrienes." (PMID 30333826, 2018). "Interestingly, irradiation-induced overexpression of growth arrest and DNA damage inducible protein alpha (Gadd45a) inhibits the nuclear translocation of β-catenin, resulting in a downregulation of MMP9, an increase in E-cadherin and a delayed medulloblastoma tumor development." (PMID 30134800, 2018). "Thus, MMP-9 inhibition decreases tumor growth in both xenograft and syngeneic model settings." (PMID 30500835, 2018). "However, the expression of MMP8 and MMP9 can also be detected in tumor cells in patients with PDAC." (PMID 29515771, 2018).